SEC23A (SEC23 homolog A, COPII component)
Diseases named in the same sentence as SEC23A in open-access papers (continued):
Sharing a sentence is not in itself a finding about the gene and the disease.
gastric cancer (3 papers, 2023 to 2026). A primary or metastatic malignant neoplasm involving the stomach. "SEC23A overexpression has been linked to a poor prognosis in bladder and gastric cancers." (PMID 37670384, 2023). "We demonstrated that SEC23A was upregulated in gastric cancer and predicted poor prognosis in patients with gastric cancer." (PMID 37670384, 2023). "The expression of SEC23A in gastric cancer was analyzed by using qRT-PCR, western blotting and IHC staining." (PMID 37670384, 2023). "Furthermore, we identified SEC23A attenuated 5-FU therapeutic effectiveness in gastric cancer cells through autophagy-mediated ER stress relief." (PMID 37670384, 2023). "However, the role of SEC23A in gastric cancer remains unclear." (PMID 37670384, 2023). "We reveal an ER stress-SEC23A-autophagy negative feedback loop that enhances the ability of gastric cancer cells to resist the adverse survival environments." (PMID 37670384, 2023). "The ER stress-SEC23A-autophagy negative feedback loop may help gastric cancer adapt to the unfavorable survival environments during its development by alleviating ER stress, which represent a potential target for inhibiting GC progression." (PMID 37670384, 2023).
lentivirus infection (2 papers, 2020 to 2022). Virus diseases caused by the Lentivirus genus. "Stable Sec23a interference or overexpression was achieved by lentivirus infection, and confirmed by RT-qPCR and Western blot, respectively." (PMID 35236368, 2022). "Then stable S100A8 interference was achieved by lentivirus infection in cells that expressed high levels of Sec23a." (PMID 32811814, 2020).
medullary thyroid carcinoma (2 papers, 2018 to 2019). "In thyroid medullary carcinoma, miR-375 was also down-regulated and associated with metastasis possibly by targeting SEC23A." (PMID 30379973, 2018). "In addition, reduced SEC23A expression increased sensitivity of medullary thyroid carcinoma to vandetanib treatment, all of which suggest that SEC23A could be a tumor suppressor gene, indicating opposing roles for SEC23A and SEC23B in cancer, although their role in cells is interchangeable in vivo." (PMID 31595159, 2019).
skin cutaneous melanoma (2 papers, 2020 to 2022). "Furthermore, TCGA data mining and analysis show that Sec23a is a favorable diagnostic and prognostic marker for human skin cutaneous melanoma." (PMID 35236368, 2022). "Furthermore, TCGA data mining and analysis show that Sec23a is a favorable diagnostic and prognostic marker for human skin cutaneous melanoma (SKCM)." (PMID 35236368, 2022). "Kaplan–Meier plots analysis revealed that skin cutaneous melanoma (SKCM) patients with high Sec23a expression levels had significantly better overall survivals in comparison with patients with low Sec23a expression level." (PMID 35236368, 2022). "We demonstrate that higher Sec23a and Atg5 expression levels appear to be protective factors and favorable diagnostic (TNM staging) and prognostic (overall survival) markers for skin cutaneous melanoma (SKCM) and colon adenocarcinoma (COAD) patients." (PMID 32811814, 2020). "Sec23a and Atg5 expression level were both significantly lower in skin cutaneous melanoma (SKCM) patients with advanced primary tumors and regional lymph node metastasis in comparison with SKCM patients of early stages." (PMID 32811814, 2020).
bladder tumor (1 paper, 2021). "SEC23A expression in advanced bladder tumor samples was significantly higher than that in early stage tumor samples (T1+2 vs T3+4, N0 vs N+, Stage I + II vs Stage III + IV; p < 0.05)." (PMID 34456965, 2021).
colon adenocarcinoma (1 paper, 2020). "In colon adenocarcinoma (COAD), similar with SKCM, there was also an inverse-relationship between Sec23a and Atg5 expression and the TNM stages and overall survivals." (PMID 32811814, 2020).
erythroleukemia (1 paper, 2021). Acute erythroid leukemia characterised by the presence of at least 50% erythroid precursors and at least 20% myeloblasts in the bone marrow. "To determine whether SEC23A also functionally compensates for SEC23B deficiency in human erythroid cells, we first generated clonal human erythroleukemia K562 cell lines that are deficient in SEC23B using CRISPR-Cas9 genome editing." (PMID 34818036, 2021).
lung carcinoma (1 paper, 2016). "miR-375 has been shown to target YAP1 in lung cancer cells and also SEC23A at its 3′-UTR in PC cell lines to regulate cell growth." (PMID 27832783, 2016).
meningioma (1 paper, 2020). A generally slow growing tumor attached to the dura mater. "Grade-wise comparisons on MGI (benign) vs MGII (atypical) meningiomas revealed prominent involvement of TIMM50, SEC23A, MTAP, RPS23, and ADRM1 based on the concordance analysis of highly ranked features from across 20 Machine Learning randomized iterations obtained via the methods of the Ball group." (PMID 32974197, 2020).
metastatic tumors (1 paper, 2024). "Intriguingly, the obtained results from our in vitro and ex vivo validation were in concordance with other studies that reported TINAGL1 as a Sec23a-dependent metastasis suppressor being upregulated in metastatic tumors." (PMID 38637790, 2024).
pancreatic cancer (1 paper, 2025). "Under the effect of ceRNA regulation, cascades ADAM12, MET, QKI, SEC23A, and ZEB2 were reported as PDAC disease signatures that significantly impacted the survival rates of pancreatic cancer patients." (PMID 40728965, 2025).
sickle cell disease (1 paper, 2021). Sickle cell anemias are chronic hemolytic diseases that may induce three types of acute accidents: severe anemia, severe bacterial infections, and ischemic vasoocclusive accidents (VOA) caused by sickle-shaped red blood cells obstructing small blood vessels and capillaries. "Therefore, genetic strategies aimed at increasing SEC23A levels therapeutically for CDAII may be performed exclusively in erythroid cells, limiting the possibility of complications in other cells, as recently shown for other erythroid disorders such as sickle cell disease." (PMID 34818036, 2021).
thyroid (1 paper, 2016). "This approach identified SEC23A as a bona fide miR-375 target, which we validated by immunoblotting and immunohistochemistry of non-tumor and pathological thyroid tissue." (PMID 27036030, 2016).
thyroid carcinomas (1 paper, 2016). "Immunohistochemical analysis of thyroid tissues confirmed the decreased in SEC23A cytoplasmic expression in MTC sections and C-cells when compared to non-tumor tissues and non-MTC thyroid carcinomas." (PMID 27036030, 2016).
thyroid tumor (1 paper, 2016). A benign or malignant neoplasm affecting the thyroid gland. "Together, these results demonstrated that the miR-375/SEC23A axis acts as a regulator of thyroid tumor cell proliferation and synergistically potentiates the therapeutic effect of vandetanib." (PMID 27036030, 2016).
uveitis (1 paper, 2020). An inflammatory process affecting a part of or the entire uvea. "The second cluster (C2) of genes was relatively higher expressed in JIA cases without uveitis and contained genes involved in cholesterol biosynthesis and mevalonate pathway (e.g., MVD, FDPS, SEC23A)." (PMID 33042130, 2020).
tumor (20 papers, 2014 to 2026). "Initial studies found SEC23A to be aberrantly expressed in various cancer types and demonstrated a strong association with tumor progression, metastasis, and drug resistance." (PMID 39904858, 2025). "In univariate analysis, age > 65 years, higher tumor stages, distant metastasis, positive lymph node status (N1 and N3), and the expression of SEC23A (median based) were significantly associated with worse OS." (PMID 37046730, 2023). "We propose that miR-375 over-expression associated with SEC23A down-regulation could improve the efficacy of vandetanib in targeting of tumor cells, constituting an alternative route for controlling cell proliferation." (PMID 27036030, 2016). "Functionally, high SEC23A levels promoted tumor cell proliferation and were correlated with an immunosuppressive microenvironment, characterized by increased M2 macrophage infiltration and reduced Tregs." (PMID 42052483, 2026). "In recent years, the function of SEC23A in central processes of tumor development and metastasis, including tumor cell proliferation, migration, and invasion has begun to be elucidated." (PMID 39904858, 2025). "Significant variations in SEC23A transcriptional levels were observed through bioinformatic analysis using data from TCGA and GTEx across 33 different tumor types." (PMID 39904858, 2025). "Although we expanded this from gene expression toward protein expression, conclusions on the precise role of SEC23A in tumor biology and especially direct or indirect effects on immune cells in STAD need further analyses, with a focus on cellular assays." (PMID 37046730, 2023). "Our findings in human tissue samples and public databases revealed a significantly higher expression of SEC23A in STAD than in tumor adjacent normal tissues." (PMID 37046730, 2023). "In line with this, the SEC23A gene was shown to be involved in the regulation of metastases of different tumor types; however, its expression and activity have not yet been elucidated in STAD." (PMID 37046730, 2023). "Under 5-FU treatments, SEC23A knockdown inhibited tumor growth, as demonstrated by the volume and weight of tumors." (PMID 37670384, 2023). "Since the first report on the inhibitory role of Sec23a in cancer metastasis, mechanistic investigations have been focused on remodeling of tumor microenvironment by Sec23a-regulated cancer cell secretome at the site of distant metastasis." (PMID 35236368, 2022). "Second, prior to this study, only the tumor suppressor function of SEC23A has been reported in preclinical studies when SEC23A was the target gene of miRNAs." (PMID 34456965, 2021). "The colonization capacity in vitro of tumor cells with altered Sec23a expression was evaluated via soft agar colony formation assay." (PMID 32811814, 2020). "Our study reveals for the first time an alternative mechanism of autophagy activation by SEC23A in tumor cells, i.e, through the secretory protein pathway." (PMID 32811814, 2020). "The formation of autolysosomes and autolysosomes analyzed by TEM were markedly reduced in tumor cells with Sec23a interference and augmented in tumor cells with Sec23a overexpression." (PMID 32811814, 2020). "And SEC23A has been reported to participate in chondrogenesis and suppress tumor metastasis by regulating tumor cell protein secretion, i.e., the secretome." (PMID 32811814, 2020). "In summary, we demonstrated that over-expression of miR-375 in MTC resulted in decreased SEC23A protein expression in tumor tissue." (PMID 27036030, 2016). "Tumor tissues from these mice were subjected to immunohistochemical staining to detect the expression of Sec23A." (PMID 27495250, 2016). "Therefore, if the expression level of SEC23A can be inhibited, it can block tumor stem cell renewal." (PMID 40042106, 2025). "Since the relationship between SEC23A expression and drug sensitivity has been confirmed in several tumor entities, we investigated whether this factor also influences CRC patients’ prognosis." (PMID 39904858, 2025).
tumor (continued). "SEC23A expression was positively correlated with the tumor’s pT stage." (PMID 37046730, 2023). "The SEC23A gene is involved in the occurrence and development of various tumor entities." (PMID 37046730, 2023). "This in turn suggests that SEC23A itself might also act as a tumor-promoting gene, at least in STAD." (PMID 37046730, 2023). "Similarly, we verified the initial bioinformatics results of SEC23A expression only in a small cohort of tumor samples." (PMID 37046730, 2023). "The tumor volume and weight showed that SEC23A knockdown could inhibit tumor growth and enhance MKN45 cells sensitivity to ER stress in vivo." (PMID 37670384, 2023). "While knockdown of CDK6, ZEB1, and Sec23a expression compromised mammosphere formation, tumor cell migration, and/or clustering of MDA-MB-231 cells, only siCDK6 partially mimicked siICAM1 in inhibiting lung colonization of MDA-MB-231 cancer cells within 7 days after tail vein injection." (PMID 34381029, 2021). "By conducting multi-dimensional analysis, we ruled out remodeling of the tumor microenvironment (TME) by the SEC23A-regulated secretome as the mechanism that underlies the oncogenic activity of SEC23A." (PMID 34456965, 2021). "Thus we modulated the expression of the most up-regulated miRNA, miR-375, in different tumor cell lines and identified SEC23A as a bona fide miR-375 target in MTC through a combination of in silico and experimental approaches." (PMID 27036030, 2016). "These discoveries suggest that the effect of Sec23A knockdown may be different in different cell lines or stages of tumor." (PMID 27495250, 2016). "Moreover, SEC23A has been identified as a principal regulator of the ER stress response, a cellular process that plays a pivotal role in the survival and drug resistance of tumor cells." (PMID 39904858, 2025). "Thus, Sec23a is the initiator of the tumor‐suppressive activity of the Sec23a‐dependent secretome." (PMID 37356089, 2023). "Inhibition of SEC23A expression reduces its protein translation level, thus primarily affecting the assembly of COPII, but also, more generally, the protein secretion of tumor cells, and can thereby contribute to a reshaping of the tumor microenvironment." (PMID 37046730, 2023). "Since the well-characterized function of SEC23A is its regulation of secretory proteins, we investigated whether SEC23A expression is associated with TME remodeling by examining the matrix deposit (the Stromalscore) and tumor-infiltrating immune cells (TIIC, the Immunescore) in BLCA." (PMID 34456965, 2021). "To evaluate the effect of Sec23a expression status on metastatic colonization efficiency in vivo, we inoculated OL-shSec23a, POL-Sec23a-OE, and control tumor cells to NOD/SCID mice by tail vein injection." (PMID 32811814, 2020). "Among these were several genes with known tumour suppressor activity (e.g. FLNA, FBLN1, MYL9, CLIC4 and SEC23A)." (PMID 27124473, 2016). "Using immunoblotting and immunohistochemistry, we confirmed the under-expression of SEC23A in the presence of miR-375 in TT cells and in MTC compared to non-tumor adjacent thyroid tissue." (PMID 27036030, 2016). "Over-expression of miR-21 promoted tumor growth in BALB/c nude mice and suppressed tumor expression of Sec23A." (PMID 27495250, 2016). "SEC23A, a member of the coatomer protein complex II (COPII) machinery, is instrumental in altering the tumor cell secretome in various cancers." (PMID 27832783, 2016). "Despite previous research indicating a potential role for SEC23A in specific tumor cell types, our findings did not reveal any statistically significant variations in both cell cycle phase distribution and proliferation rates between CRC cells with varying SEC23A expression levels." (PMID 39904858, 2025). "However, secretome-independent role of Sec23a in regulation of tumor metastasis has not been reported." (PMID 35236368, 2022).
tumor (continued). "A total of 139 EC tumor tissues were used to show the positive correlation between the expression of RBM25 and PSI value of SEC23A-27345-AP and ZNF638-53926-AP and the negative correlation between RBM25 and PSI value of SEC23A-27346-AP and ZNF638-53927-AP." (PMID 34676158, 2021). "To understand the mechanism of this differential effect, we found that ferroptosis inducers upregulate mRNAs encoding multiple direct and indirect autophagy stimulators, such as ATG16L2, ATG9A, ATG4D, GABARAP, SQSTM/p62, SEC23A and BAX, in tumor cells growing in 2D but not in 3D culture." (PMID 37658069, 2023).
cancer (13 papers, 2016 to 2025). A tumor composed of atypical neoplastic, often pleomorphic cells that invade other tissues. "We have identified a new mechanism underlying the inhibitory effect of Sec23a on cancer metastasis." (PMID 34421345, 2021). "Finally, we analyzed the impact of this miR-375/SEC23A axis on cell proliferation and viability especially in association with vandetanib, a clinically relevant cancer drug for treatment of metastatic MTC patients." (PMID 27036030, 2016). "However, the mechanism underlying SEC23A regulation of human cancer progression remains largely unknown." (PMID 34456965, 2021). "The relationship between drug treatment, resistance development, and alterations in SEC23A expression levels in cancer cells has been described previously." (PMID 39904858, 2025). "Using SEC23A, a gene with limited mechanistic understanding in human cancer as an example, we illustrated the validity and effectiveness of this approach to derive new mechanistic understandings underlying its prognostic significance." (PMID 34456965, 2021). "Several cancer-associated mRNAs were found using the RISCTRAP assay, including ICAM1, SUMO3, HIF1A, and SEC23A." (PMID 34831007, 2021). "Future studies are required to elucidate the biological processes regulated by SEC23A and their respective role in cancer initiation and progression." (PMID 34456965, 2021). "First, this is the first study to demonstrate that SEC23A mRNA expression is associated with the OS, DSS, and PFI in different cancers such as ACC, BLCA, CESC, KIRP, and UVM patients." (PMID 34456965, 2021). "We performed an in-depth bioinformatics analysis to evaluate the prognostic value of SEC23A in human cancers." (PMID 34456965, 2021). "Potentially, overexpression of miR-375 in PC cells directly inhibits production of SEC23A, which prevents the secretion of metastasis-suppressive proteins, thus enabling the metastatic spread and colonization of the cancer cells." (PMID 27832783, 2016). "Cancer stem cells can use the SEC23A/ER stress/FAM134B/ER phagocytosis axis for self‐renewal." (PMID 40042106, 2025). "The dual function of SEC23A in both vesicle transport and the stress response suggests that it may be a pivotal factor in determining the fate of cancer cells under chemotherapeutic stress." (PMID 39904858, 2025). "Here, SEC23A expression was also significantly increased in the cancer tissues." (PMID 37046730, 2023). "Although we did not confirm whether in STAD the pro-tumoral activity of SEC23A is also executed via MAPK signaling, our results strengthen the double-edged sword character of SEC23A for human cancer." (PMID 37046730, 2023). "SEC23A, a regulator of secretory protein function, plays an important role in human cancer." (PMID 34456965, 2021). "miR-1227 and inhibition of SEC23A may prove to be valuable research tools to dissecting the specific roles of L- and S-EV in cancer metastasis." (PMID 34831007, 2021). "Interestingly, SEC23A and SEC23B are associated with autophagy, which is involved in cancer development and progression." (PMID 31595159, 2019). "SEC23 protein has two isoforms (SEC23A and SEC23B) and their aberrant expression and mutations were reported to cause human diseases and oncogenesis, whereas SEC23A and SEC23B may have the opposite activity in human cancer, for a reason that remains unclear." (PMID 31595159, 2019). "Therefore, both SEC23A and SEC23B have vital functions in human beings, loss of which would cause serious diseases; particularly, lost SEC23B closely associated with Cowden syndrome, which has potentially cancer predisposing." (PMID 31595159, 2019). "By bioinformatically analyzing the expression levels of SEC23A among various cancers in TCGA and GTE-x, the transcriptional levels of SEC23A were found to be divergent in 33 tumors." (PMID 37046730, 2023). "Sec23 homolog A (SEC23A), a core component of coat protein complex II (COPII), has been reported to be involved in several cancers." (PMID 37670384, 2023).